RNU6-829P (RNA, U6 small nuclear 829, pseudogene)
Gene: Small nuclear RNA gene on chromosome 9 (93,375,556 to 93,375,667, forward strand). Ensembl gene ENSG00000200570.
Homologues: Orthologues: macaque U6 (94% identical), guinea pig U6 (57% identical). Paralogues in human: RNU6-166P (81% identical), RNU6-1019P (80% identical), RNU6-1060P (80% identical), RNU6-1024P (79% identical), RNU6-338P (79% identical), RNU6-41P (79% identical), RNU6-47P (79% identical), RNU6-657P (79% identical), RNU6-820P (79% identical), RNU6-949P (79% identical), RNU6-1152P (79% identical), RNU6-116P (79% identical), and 1283 more.